STAT3 (signal transducer and activator of transcription 3)
Diseases named in the same sentence as STAT3 in open-access papers (continued):
Sharing a sentence is not in itself a finding about the gene and the disease.
Cachexia (continued). "This study demonstrates the systemic effect of LIF on cachexia, and reveals that LIF overexpression disrupts hepatic de novo lipogenesis via the STAT3/PPARα axis as an important underlying mechanism." (PMID 38245529, 2024). "As far as we know, no available studies evaluate the biological effects of STAT3 inhibition on cancer-induced cachexia in one experimental model." (PMID 33158194, 2020). "In contrast to skeletal muscle, increased liver STAT3 activity was independent of cachexia severity in the ApcMin/+ mouse." (PMID 27449092, 2016). "Cachexia progression further increased STAT-3 phosphorylation, though there was no change in liver gp130 and albumin protein content with cachexia progression." (PMID 25789991, 2015). "For example, the collaboration between STAT3 and NF-κB pathways has been shown to modulate IFN-γ/TNF-α-induced muscle wasting, suggesting that inflammatory signaling acts through integrated networks of downstream effectors, such as STAT3 and NF-κB to induce cachexia." (PMID 30081609, 2018). "However, apart from its early induction in the weight—stable cancer mice, no further increase was observed in SOCS-3 with cachexia progression, highlighting a disconnect between STAT-3 and its downstream negative regulator with chronic IL-6 signaling." (PMID 25789991, 2015). "However, in our study, treatment of STAT3 inhibitor has decreased RVSP in the PAH rat model, without significant changes, which could be explained by severe PAH with the cachexia model used in our study." (PMID 35524286, 2022).
depression (66 papers, 2014 to 2026). "In contrast, upregulation of miR‐204‐5p in the vmPFC of CUMS rats significantly causes inhibition of JAK2/STAT3 signaling pathway, improvements in neuronal impairments, and an abolition of the depression and anxiety‐like behaviors." (PMID 39792918, 2025). "A previous study shows microglia-specific STAT3 is associated with depression-like behaviours in mice." (PMID 35508467, 2022). "Multiple therapeutic targets were mediated by active ingredients of XYS, such as IL2, IL4, IL6, IL10, and STAT3, which are involved in immune and inflammatory responses closely associated with depression." (PMID 32256358, 2020). "STAT3, a transcription factor central to diverse biological processes including cell proliferation, differentiation, apoptosis, and immune regulation, has been implicated in the pathophysiology of major depressive disorder (MDD)." (PMID 40699741, 2025). "In light of the reported association between STAT3 signalling and mental illnesses, we next subjected STAT3 KO mice to extensive behavioural testing, with a particular focus on paradigms examining emotional behaviours relevant to depression." (PMID 33046834, 2021). "Indeed, a close association between STAT3 signaling, stress, and depression have been reported." (PMID 41428145, 2025). "The IL-6/STAT3 pathway has been shown to facilitate the formation of neuropathic pain and comorbid depression in spinal nerve injury (SNI) rats." (PMID 40093024, 2025). "Animal studies have indicated that the IL-6/STAT3 signaling pathway is involved in depression-like behaviours and that STAT3 controls IL-6-dependent SERT expression." (PMID 40115872, 2025). "We further investigated the effects of WP1066, a JAK2/STAT3 inhibitor, on neuroinflammation and depression-like behaviors induced by CUS." (PMID 39864626, 2025). "One of the key contributors to refractory depression is the dysregulation of the JAK2/STAT3 signaling pathway." (PMID 39864626, 2025). "In summary, our results describe for the first time a relationship between SI and the IL-6-induced stimulatory capacity of the STAT3-expressing PBMCs in the context of depression." (PMID 40115872, 2025). "Based on experimental data, therapy focused on IL-6/STAT3 signaling should be a suitable target for anti-cancer therapy because it can also influence other aspects of malignant disease, such as wasting and depression." (PMID 38715108, 2024). "This regulation, dependent on STAT3, provides a potential neurobiological basis for the involvement of IL-6 in depression." (PMID 37938494, 2023). "We next evaluated if the target genes of STAT3 were changed during the occurrence of depression and C3aR blockade." (PMID 35715851, 2022). "Next, we observed the role of p-STAT3 in the Acp5 expression following the acquisition of comorbidity of neuropathic pain and depression." (PMID 35690777, 2022). "Our study also demonstrates that C3aR-APT2/DHHC7 palmitoylation-mediated STAT3 activation and synaptic pruning are involved in the pathophysiology of depression." (PMID 35715851, 2022). "Bai’s study showed that the levels of p-JAK1/JAK1 and p-STAT3/STAT3 were significantly decreased in the hippocampal tissue of the depression rats." (PMID 36686689, 2022). "We then investigated the underlying mechanism of C3/C3aR signaling pathway in synaptic pruning and palmitoylation cycle-mediated STAT3 activation in depression-like animals." (PMID 35715851, 2022). "According to previous findings, interleukin-6 elevates STAT3 levels and promotes depression by increasing serotonin transporters (SERT)." (PMID 35164154, 2022). "In the present study we also show that Li+ inhibits activation of NLRP3 inflammasome and improves motor behaviour, cognition and depression by stimulating STAT3." (PMID 35115638, 2022).
depression (continued). "IL-6 and STAT3 have been previously shown to be involved in serotonin transporter function and depression-like behavior." (PMID 32998701, 2020). "ROS-activated ABL1 mediates inflammation through regulating NF-κB1 and STAT3, which subsequently leads to the development of GC and GC-related depression." (PMID 31396300, 2019). "The blockade of STAT3 activation in the hippocampus and in the hypothalamus attenuated depression-like behavior and anorexia in mice suffered neuroinflammation, respectively." (PMID 31213027, 2019). "These protein targets, especially hubs, and the functional nodes, MTOR, CDK6, SHC1, RCOR1 CCNA2 and STAT3, have been already reported to be involved in depression." (PMID 28954415, 2017). "In PPIN, the main hubs such as AKT1, JUN, MAPK8 and STAT3 have already been reported to be involved in depression." (PMID 28954415, 2017). "STAT3 IL6-dependently associated with the SERT promoter and inhibition of STAT3 blocked the effect of IL6 in-vitro and modulated depression-like behavior in-vivo." (PMID 25760924, 2015). "Collectively, these results provide robust evidence that the miR‐204‐5p/JAK2/STAT3 pathway may critically involve in the pathogenesis of depression, which may serve as potentially critical therapeutic target in the treatment of MDD." (PMID 39792918, 2025). "In summary, these results provide important, new insights into the mechanisms of the miR‐204‐5p/ JAK2/STAT3 signaling pathway that may be involved with depression and may thus serve as a potential new target for the prognosis and treatment of this condition." (PMID 39792918, 2025). "This process disrupts the activation of the IL-6/STAT3 signaling pathway, alleviating neuroinflammation by suppressing proinflammatory mediators, while enhancing synaptic plasticity ultimately ameliorates depression-like behaviors." (PMID 40949123, 2025). "Previous study demonstrated that intracerebroventricular administration of IL-6 induces depression-like behavior by activating STAT3-dependent regulation of serotonin transporter function, highlighting the interplay between IL-6 elevation and STAT3 signaling in mood dysregulation." (PMID 41428145, 2025). "In conclusion, this study provides a novel antidepressant mechanism for agomelatine, STAT3-related downstream molecules regulated by agomelatine may become new therapeutic targets for the rapid treatment of depression." (PMID 41428145, 2025). "The study of whether ghrelin regulates neuroinflammation when activating the Jak2/STAT3 pathway will be an important basis for comprehensively determining whether ghrelin can be used as a target for the treatment of depression." (PMID 39057075, 2024). "Regarding the statistically significant correlation between HDRS and measured parameters, reducing HDRS and relieving depression symptoms might lead to a reduction in IL-6, STAT3, NLRP3, and an elevation in AMPK." (PMID 38855751, 2024). "Induction of nuclear factors Nrf2, SOCS3/STAT3, and inhibition of apoptosis may also be involved in the Zn and Se neuroprotective effect on memory recovery and prevention of anxiety/depression-like behavior on a long-term post-reperfusion." (PMID 38707461, 2024). "The JAK2/STAT3 and NF‐κB pathway have been well described in depression." (PMID 37032645, 2023). "Likewise, in the chronic stress-induced depression mice, the pSTAT3/STAT3 ratio increased in the prefrontal cortex." (PMID 35715851, 2022). "The results also indicated that Gypenoside XVII from Gypenosides could regulate the complement system by attenuating the changes in the C3/C3aR/STAT3 signaling pathway and thus inhibiting synaptic pruning in stress-induced depression." (PMID 35745148, 2022). "Besides, the immunofluorescence detected the high co-localization of APT2-pSTAT3 and DHHC7-STAT3 in response to chronic stress, indicating that the palmitoylation cycle induces STAT3 signaling in depression." (PMID 35715851, 2022).
depression (continued). "Taken together, the IL6/STAT3/Acp5 pathway modulated the excitability of PrL pyramidal neurons to change the adaption of PrL region, which critically involved in the development of comorbidity of neuropathic pain/depression." (PMID 35690777, 2022). "Additionally, STAT3 was found to associate with the SERT promoter in an IL-6-dependent manner, with the inhibition of STAT3 blocking the effect of IL-6 on 5-HT uptake in vitro and reducing depression-like behavior in vivo." (PMID 34571919, 2021). "The STAT3/SOCS3 pathway has been suggested to be involved in the pathogenesis of depression." (PMID 33833401, 2021). "Further investigation will be necessary to disentangle whether activation of STAT3 signaling in microglia, astrocytes, or both cell types, promotes depression-like behavior during withdrawal from chronic alcohol exposure." (PMID 34016951, 2021). "For example, Sun-Ho Kwon and his colleagues knocked out STAT3 in CNS and reported that depression-related behaviors were regulated by cytokines; they further speculated that the inhibition of STAT3 could be a potential therapeutic strategy for depression." (PMID 32655424, 2020). "Depression of HOST2 suppressed STAT3-mediated proliferation and migration in TNBC cells." (PMID 32248842, 2020). "However, there are conflicting views on the influence of IL-6 on STAT3 in the regulation of depression as well as glucose homeostasis." (PMID 32655424, 2020). "The role of STAT3 in both ketamine’s mechanism of action and in depression pathophysiology remains unclear." (PMID 31827434, 2019). "Finally, we set-out to examine the direct involvement of STAT3 in depression-like behavior and found that – as expected – pharmacological inhibition of STAT3 elevated SERT expression and reduced depression-like behavior in wild-type mice." (PMID 25760924, 2015). "Here we tested the hypothesis that IL6-induced modulation of serotonergic neurotransmission through the STAT3 signaling pathway contributes to the role of IL6 in depression." (PMID 25760924, 2015). "Both STAT3 and pSTAT3 have been shown to be localized to synaptic sites in the hippocampus and cortex and, independent of nuclear localization, to play a role in long-term depression, a form of synaptic plasticity essential for normal CNS function." (PMID 25177271, 2014). "Hence, we used chronic social defeat stress (CSDS) as an animal model of depression, to investigate whether synaptic plasticity impairment in depression, improved by agomelatine, is mediated through the STAT3 mechanism." (PMID 41428145, 2025). "Thus, we hypothesized that miR‐204‐5p may regulate neuroinflammation and apoptosis via the JAK2/STAT3 signaling pathway, a relationship which may then be targeted for use in alleviating depression." (PMID 39792918, 2025). "We used, WP1066 or SC99, two inhibitors of the JAK2/STAT3 pathway capable of crossing the blood‐brain barrier and thus achieving therapeutic effects within the central nervous system (CNS), to evaluate the contribution of this pathway to the display of depression." (PMID 39792918, 2025). "Moreover, the mechanism of Glycogen synthase kinase 3β (GSK3β), regulated by signal transducer and activator of transcription 3 (STAT3), may play an important role in the synapse-related pathological mechanisms of depression." (PMID 41428145, 2025). "JAK2/STAT3 and NF‐κB signaling system may be new targets for depression treatment, and intervening in their activation pathway, it also has positive implications for the treatment of depression." (PMID 37032645, 2023). "Activation of the HMGB1/signal transducer and activator of transcription 3 (STAT3)/nuclear factor-kappa B (NF-κB) p65 axis in microglia located in the medial prefrontal cortex (mPFC) facilitates microglial activation and autophagy, contributing to the pathophysiology and progression of depression." (PMID 38026940, 2023).
depression (continued). "However, it is unknown whether STAT3 in the hippocampus regulates expression of immune response genes and development of depression-like behaviors during ethanol withdrawal after chronic exposure." (PMID 34016951, 2021). "Clinical studies (NCT00291239; NCT03080025) are investigating the role of IL-6 as a biomarker or causative molecule in depression, but none are investigating STAT3 or oncostatin M. It should be noted that STAT3 is activated by elevated IL-6 and oncostatin M belongs to the IL-6 family." (PMID 32998701, 2020). "Taking both clinical and experimental data from in vivo and in vitro studies together, ROS mediate the activation of ABL1 to promote cytokine release by triggering NF-κB and STAT3, which may partially account for the poorer prognosis of GC patients with depression." (PMID 31396300, 2019). "Our findings reveal that DSS mitigates hippocampal neuroinflammation and enhances hippocampal neurogenesis in depression model mice via modulation of the TLR4/NF-κB p65, JAK2/STAT3 and AKT-GSK3β signaling pathways." (PMID 41190144, 2025). "Moreover, STAT3 overexpression was found to ameliorate hTau-associated synaptic deficits in an Alzheimer’s disease model, suggesting that STAT3 may influence depression through multiple, context-dependent mechanisms involving oxidative stress, synaptic regulation, and neuroinflammation." (PMID 41428145, 2025). "Among the top 10 hub gene targets, MAPK1, AKT1, PIK3R1, EGFR, STAT3, and SRC were the most enriched targets in the selected KEGG pathway, suggesting their critical role in the pathogenesis of depression." (PMID 38505421, 2024). "IL-6 triggers the JAK/STAT3 signaling cascade and modulates activation of the HPA axis in depression; thus, increasing IL-6 levels contributes to depression." (PMID 36648973, 2023). "For example, lithium chloride, a mood stabilizer used in the treatment of bipolar disorder and treatment-resistant major depressive disorder, inhibits STAT3 activation in astrocytes and reduces JAK-STAT3 signaling activity." (PMID 37938494, 2023). "Over-expression of miR-9-5p in MDD mice enhanced M1 polarization and increased depression-like behavior by suppressing SOCS2 expression and activating the JAK/STAT3 pathways; conversely, miR-9-5p inhibition alleviated depression in MDD mice." (PMID 36613914, 2022). "The results showed that sodium valproate can improve the depression-like and cognitive dysfunction of rats after chronic restraint stress by activating the JAK1/STAT3 pathway and inhibiting the activation of inflammatory factors." (PMID 35148670, 2022). "Basic studies demonstrated that modified BXXXD, a formula similar to GJHQHLRSD, can effectively alleviate UC as well as relieve depression and UC through targeting VEGFA, TNF, STAT3, EGFR, and others." (PMID 34539797, 2021). "Targeting STAT3 pharmacologically has the potential to dampen an overactive neuroimmune response in AUD and treat comorbid AUD and depression in humans." (PMID 34016951, 2021). "STAT3 is one of the transcription factors regulating the production of the cytokine IL-6, IL-10, TNF-α, and IL-1β, which have been shown to be involved in depression." (PMID 32655424, 2020). "To probe the potential mechanism of the occurrence of depression, we also detect the expression of ABL1, NF-κB1, STAT3, IL-6, IL-1β, and COX2 in the hippocampus of depressive mice." (PMID 31396300, 2019). "PPI network analysis identified core targets such as MAPK3, STAT3, AKT1, PRKACA, MAPK1, and TNF, suggesting BCBL's efficacy in depression treatment may stem from its action on multiple key targets." (PMID 40909251, 2025).
depression (continued). "Echinacoside ameliorates depression-like behavior in CUMS mice, possibly through enhancing BDNF-CREB pathway and inhibiting neuroinflammation via regulating microglia M1/M2 polarization and JAK1/STAT3 pathway." (PMID 36686689, 2022). "Depression was not shown to influence STAT3 activation in an ex vivo model of regional ischaemia/reperfusion in hearts isolated from Sprague-Dawley rats exposed to experimental depression induced by chronic mild stress." (PMID 30424579, 2018). "MiR-532-5p alleviates depression-like behaviors in CUMS-exposed mice by suppressing the expression of IL-6, interleukin-1 beta (IL-1β), TNF-α, and monocyte chemoattractant protein-1 through inhibition of the signal transducer and activator of transcription 3 pathway." (PMID 40949123, 2025). "Taken together, these data demonstrate that the IL-6/STAT3 signaling pathway plays an important role in depression or depression-like behavious, and targeting this pathway may provide a novel therapeutic approach for the treatment of this disorder." (PMID 40115872, 2025). "Furthermore, ghrelin/GHSR can activate multiple signaling pathways, including cAMP/CREB/BDNF, PI3K/Akt, Jak2/STAT3, and p38-MAPK, to produce antidepressant effects, given which it is expected to become a potential therapeutic target for the treatment of depression." (PMID 39057075, 2024). "In conclusion, taVNS ameliorates depression‐like behaviors in CUMS model rats, inhibits the hypothalamic microglia activity and increases α7nAchR expression in the hypothalamus, which in turn activates the JAK2/STAT3 signaling pathway and inhibits the NF‐κB signaling pathway." (PMID 37032645, 2023). "Kaempferol and quercetin had been reported to relieve symptoms of depression and exhibited antidepression effects through acting on interleukin-6 (IL6), mitogen-activated protein kinase 1 (MAPK1), signal transducer, and activator of transcription 3 (STAT3) and transcription factor AP-1 (JUN)." (PMID 36045654, 2022). "Additionally, applying STAT3‐IN‐12 in ICH mice brought depression‐related behaviors closer to those observed in the control group (P > 0.05), suggesting that targeting the JAK‐STAT pathway may alleviate the severity of depression in mPFC‐ICH." (PMID 38946585, 2024).